YBX1 (Y-box binding protein 1)
Diseases named in the same sentence as YBX1 in open-access papers (continued):
Sharing a sentence is not in itself a finding about the gene and the disease.
lung adenocarcinoma (38 papers, 2015 to 2026). A carcinoma that arises from the lung and is characterized by the presence of malignant glandular epithelial cells. "LINC00312 can directly bind to the transcription factor Y-Box binding protein 1 (YBX1) to increase the average density of VM in lung adenocarcinoma tissue, thereby causing tumor neovascularization." (PMID 38152110, 2023). "In lung adenocarcinoma cells, the silencing/overexpression of YBX1 caused a simultaneous change in MUC1, and MUC1 overexpression partially reversed the decreased tumor cell migration, aggressiveness, and stemness caused by YBX1 silencing." (PMID 34976785, 2021). "Moreover, we found that high YBX1 expression in lung adenocarcinoma is associated with poor prognosis and metastasis in patients." (PMID 34976785, 2021). "Another proposed mechanism for gefitinib resistance links MVP with Y-box binding protein 1 (YB-1) in lung adenocarcinoma HCC827 and PC-9 cells." (PMID 40004027, 2025). "Previous study also revealed that LINC00312 induces lung adenocarcinoma metastasis and vasculogenic mimicry through directly binding to YBX1." (PMID 39789501, 2025). "The direct interaction between LINC00312 and YBX1 ultimately leads to increased migration, invasion, and VM formation in lung adenocarcinoma A549 cells." (PMID 40277941, 2025). "CircMET binds to the RBP YBX1 in lung adenocarcinoma, blocking YBX1’s interaction with IL-2 mRNA and suppressing IL-2 translation, which further illustrates how circRNA-RBP interactions disrupt cytokine production and T cell activation." (PMID 41425089, 2025). "LINC00472 inhibits lung adenocarcinoma migration and invasion by binding to YBX1 and regulating cell stiffness." (PMID 40799245, 2025). "LINC00312 plays a crucial role in inducing VM in lung adenocarcinoma by directly interacting with YBX1, a transcription factor involved in various cellular processes including angiogenesis and cell proliferation." (PMID 40277941, 2025). "Elevated levels of both YBX1 and CDC25a proteins were observed in lung adenocarcinoma cells compared to lung fibroblasts." (PMID 38255791, 2024). "Previous work has indicated that YBX1 (or YB-1) correlates with poor survival in lung adenocarcinoma." (PMID 37381723, 2023). "Intriguingly, depletion of YBX1 has been found to decrease metastasis associated in colon cancer-1 (MACC1) promoter activity, thus abolishing MACC1/c-Met signaling in lung adenocarcinoma cells." (PMID 37381723, 2023). "In lung adenocarcinoma, YBX1 binds LINC00472, mediates changing in biophysical properties of cells and inhibits the migration and invasion of the carcinoma." (PMID 36969033, 2023). "Using the CPTAC database, we found that YBX1 protein is significantly upregulated in lung adenocarcinoma (LUAD) patients." (PMID 35410432, 2022). "We found that the expression levels of Mucin-1 (MUC1) and YBX1 were positively correlated in lung adenocarcinoma cells and lung adenocarcinoma tissue." (PMID 34976785, 2021). "In lung adenocarcinoma cell lines, YBX1 directly or indirectly activates the MUC1 promoter region from-1480 to -1476, this transcriptional regulation targets downstream metastasis and stem-like properties." (PMID 34976785, 2021). "To study the functional significance of YBX1 in lung adenocarcinoma, we first examined the migration and invasion capabilities, which are closely related to cancer metastasis and recurrence." (PMID 34976785, 2021).
lung adenocarcinoma (continued). "In the retrospective cohort study including 176 lung adenocarcinoma patients after surgery, we found that the YBX1 and MUC1 expression levels were highly correlated in lung adenocarcinoma (r=0.357, P<0.001)." (PMID 34976785, 2021). "In the 24-hour wound healing assay, we found that the silencing/overexpression of the upstream gene YBX1 played a vital role in weakening/enhancing the migration ability of lung adenocarcinoma cells." (PMID 34976785, 2021). "Our retrospective cohort study of 176 lung adenocarcinoma patients found that low coexpression of YBX1 and MUC1 was the only protective factor for DFS." (PMID 34976785, 2021). "In conclusion, LINC00472, which is lowly expressed in lung adenocarcinoma tissue, changes the biophysical properties of cells and inhibits the migration and invasion of lung adenocarcinoma cells by binding to YBX1." (PMID 33144579, 2020). "For instance, upregulated LINC00312 expression in lung adenocarcinoma tissue induces tumor metastasis and vasculogenic mimicry through direct binding to Y-Box binding protein 1 (YBX1)." (PMID 32316322, 2020). "The retrospective analysis of 116 patients with lung adenocarcinoma indicated that YBX1 was positively correlated with CDC25a expression." (PMID 27384875, 2016). "In our study, we assessed the expression of YBX1 and CDC25a in patients with complete with surgical resection of lung adenocarcinoma on basis of IASLC/ATS/ERS international multidisciplinary classification for the first time." (PMID 27384875, 2016). "We further discovered positive correlation between YBX1 and CDC25a expression (R=0.223, p=0.016) in human lung adenocarcinoma." (PMID 27384875, 2016). "Simultaneously, high expression of YBX1 or CDC25a in 116 patients with lung adenocarcinoma had shorter 5-year overall survival than low expression (5-OS%:40.5% VS 74.9%, p=0.044 and 5-OS%:45.5% VS 79.7%, p=0.004, respectively)." (PMID 27384875, 2016). "In our present study, IHC staining was performed to show the expression of CDC25a and YBX1 in 116 patients with lung adenocarcinoma." (PMID 27384875, 2016). "We analyzed the expression of YBX1 and CDC25a in 116 patients with complete surgical resection of lung adenocarcinoma by IHC staining." (PMID 27384875, 2016). "High expression of YBX1 or CDC25a protein was also observed in lung adenocarcinoma cells compared with HLF cells." (PMID 27384875, 2016). "All the evidence showed that the novel YBX1/CDC25a pathway is a potential therapeutic target for the treatment of human lung adenocarcinoma." (PMID 27384875, 2016). "In summary, YBX1 increases the promoter activity and expression of CDC25a in human lung adenocarcinoma cells." (PMID 27384875, 2016). "YBX1 was mainly presented in cytoplasm of human lung adenocarcinoma cell lines (A549, H322 and Hcc827) but little in normal human embryonic lung fibroblasts cell line (HLF)." (PMID 27384875, 2016). "Furthermore, Zhao and colleagues demonstrated that endogenous YBX1 binds to the CDC25a promoter regions, leading to increased CDC25a promoter luciferase expression in human lung adenocarcinoma cells." (PMID 40799245, 2025). "YBX1 knockdown has been shown to inhibit lung adenocarcinoma cells growth." (PMID 31481087, 2019). "Furthermore, we showed that endogenous YBX1 bound to the specific CDC25a promoter region in lung adenocarcinoma cells as compared to the HLF cells by ChIP assay." (PMID 27384875, 2016). "However, all human lung adenocarcinoma cell lines (A549, H322 and Hcc827) expressed more obvious nucleus shifting of YBX1 compared with HLF cells using immunofluorescence." (PMID 27384875, 2016).
lung adenocarcinoma (continued). "The multivariate analysis of risk factors showed that high TNM stage (HR=3.428, 95%CI: 1.519-7.737, p=0.003) and low CDC25a expression (HR=2.384, 95%CI: 1.008-7.642, p=0.048) were independent prognostic risk factors in lung adenocarcinoma but not YBX1." (PMID 27384875, 2016). "Next, we certified the assumptive mechanisms that YBX1 as the transcriptional activator to accelerate expression of CDC25a, and then the cell cycle, growth and apoptosis in human lung adenocarcinoma cells as well as the inhibition of YBX1 on the growth of xenografts in mice were tested." (PMID 27384875, 2016). "In addition, the expression of YBX1 and CDC25a from lung adenocarcinoma cells' total, nuclear and cytoplasm protein was also higher than HLF cells analyzed by Western blot assays." (PMID 27384875, 2016). "Then we demonstrated the hypothesis that CDC25a transcription activation was dependent on YBX1, which provided a new perspective mechanism on CDC25a expression regulation in lung adenocarcinoma." (PMID 27384875, 2016). "Therefore, we speculated that YBX1 affects the recurrence and metastasis of lung adenocarcinoma by regulating MUC1." (PMID 34976785, 2021). "YBX1 binds to the MUC1 promoter region (-1480bp to -1476bp) to regulate its transcription, suggesting that YBX1 promotes the occurrence and metastasis of lung adenocarcinoma via MUC1 targeting." (PMID 40799245, 2025). "Our retrospective cohort study of 176 lung adenocarcinoma patients after surgery showed that low expression of both YBX1 and MUC1 was an independent predictor of the prognosis and recurrence of lung adenocarcinoma." (PMID 34976785, 2021). "In conclusion, the low coexpression of YBX1/MUC1 showed vital prognostic significance in the prognosis and recurrence of lung adenocarcinoma." (PMID 34976785, 2021). "Similar to existing research, YBX1 or MUC1, as separate tumor markers, can predict prognosis in lung adenocarcinoma patients." (PMID 34976785, 2021). "Then we detected the expression of YBX1 and MUC1 in the cancer tissues and adjacent tissues of 6 lung adenocarcinoma patients, and we observed significantly high expression of both in the tumors." (PMID 34976785, 2021). "Analyses of YBX1 interaction networks reveal potential therapeutic targets for adenocarcinoma, while exploring PABPC1, an YBX1 interaction partner, offers avenues for discovering new drug targets in lung adenocarcinoma." (PMID 40799245, 2025). "Furthermore, we found a certain positive correlation between the expression levels of YBX1 and MUC1 (r=0.357; p<0.001) according to the IHC results of 176 lung adenocarcinoma specimens." (PMID 34976785, 2021). "Therefore, YBX1 and MUC1 are important genes that affect the occurrence, metastasis, and stemness of lung adenocarcinoma in vitro." (PMID 34976785, 2021). "Although YBX1 is exhibited as a poor prognostic factor in breast cancer, colon cancer, and ovarian cancer, it has no reported in lung adenocarcinoma by reference to new subtypes classification at present." (PMID 27384875, 2016). "In addition, we analyzed the expression of YBX1 and MUC1 in HLF cell and five lung adenocarcinoma cell lines (H358, HCC827, A549, H322, H1299), and they were significantly correlated at both the protein (r=0.8789, p=0.0057) and mRNA (r=0.9306, p=0.0018) levels." (PMID 34976785, 2021).
ovarian carcinoma (38 papers, 2011 to 2026). A malignant neoplasm originating from the surface ovarian epithelium. "In this context, “readers” such as METTL3 and VIRMA have been associated with apoptosis inhibition, migration, and invasion in ovarian cancer, while FTO leads to reduced “stemness” in ovarian cancer cell lines and YBX1 renders malignant cells susceptible to the cytotoxic effects of cisplatin." (PMID 41301911, 2025). "Moreover, re-analysis of the database revealed that high YBX1 expression is associated with poor prognosis in human breast and ovarian cancers, suggesting that YBX1 promotes cancer progression via sEVs containing tumorigenic SATII RNA." (PMID 38003589, 2023). "Previous research has indicated that YBX1 can promote homologous recombination by recognizing m5C modifications, leading to platinum drug resistance in ovarian cancer." (PMID 41523581, 2026). "First, MEG3 was reported to regulate angiogenesis in ovarian cancer endothelial cells by sponging miRNA-376a and YBX1, with significantly lower expression in ovarian cancer endothelial cells than that in normal ovarian endothelial cells." (PMID 40242248, 2025). "HIF1A-AS3 interacts with YBX1, promoting ovarian cancer tumorigenesis by inhibiting p21 and AJAP1 transcription." (PMID 40799245, 2025). "In ovarian cancer, YBX1 recognizes m5C-modified CHD3 mRNA and maintains its stability by recruiting the RNA-binding protein PABPC1, thereby enhancing homologous recombination (HR) repair and promoting resistance to platinum-induced apoptosis." (PMID 40819060, 2025). "SIAH1 as new E3 ligase, through the ubiquitin of YBX1 reversal of epithelial ovarian cancer chemotherapy drug resistance." (PMID 40799245, 2025). "Western blot analysis revealed that YBX1 knockdown decreased the protein expression of E2F1 in ovarian cancer cells, and half-life assays showed that YBX1 increased the stability of E2F1 mRNA." (PMID 38424195, 2024). "To further explore how YBX1 regulates m5C-modified RNAs, we examined the extent of YBX1 condensation in ovarian cancer cells." (PMID 38424195, 2024). "Considering that YBX1 and NSUN2 regulate E2F1 expression in ovarian cancer, we examined the role of YBX1 in ovarian cancer." (PMID 38424195, 2024). "In ovarian carcinoma-derived microvascular endothelial cells, YBX1 competes with miR-376A for binding to MEG3 (maternally expressed gene 3) lncRNA." (PMID 38255791, 2024). "We also performed polysome profiling assays in ovarian cancer cells to examine the distribution of the YBX1 protein and E2F1 mRNA in the translationally active and translationally inactive fractions." (PMID 38424195, 2024). "Azopodo-phyllotoxin SU056, a small molecule, directly binds to YBX1 and inhibits its expression, leading to cell cycle arrest and apoptosis, which has been tested in ovarian cancer cells." (PMID 38255791, 2024). "Then, we performed immunofluorescence staining with an antibody specific for YBX1 to confirm YBX1 condensation in ovarian cancer cells and found that YBX1 was concentrated in puncta in all three ovarian cancer cell lines." (PMID 38424195, 2024). "The analysis of the clinical dataset revealed that YBX1 expression is higher in cancer stroma than in normal stroma of breast and ovarian cancer tissues." (PMID 38003589, 2023). "In ovarian cancer patients, YBX1 modulates the expression of a variety of downstream targets, including CD44, thus enhancing chemoresistance." (PMID 37325635, 2023). "In addition, YBX1 was also found to resist cisplatin-induced oxidative stress in ovarian cancer cells by affecting CHD3 expression." (PMID 41522342, 2026). "Thus, our findings highlight the effect of mRNA m5C modification and the YBX1 condensation-dependent regulatory mechanism of the NSUN2-E2F1-NSUN2 loop in ovarian cancer." (PMID 38424195, 2024). "High expression of YBX1 predicted poor prognosis in ovarian cancer patients." (PMID 38424195, 2024). "Like NSUN2, YBX1 was amplified in multiple cancers, including ovarian cancer." (PMID 38424195, 2024).
ovarian carcinoma (continued). "Interestingly, microarray data (GSE4823, GSE40595) showed that YBX1 expression in breast and ovarian cancer stromal tissues was higher than that in normal stromal tissues." (PMID 38003589, 2023). "Furthermore, clinical data from The Cancer Genome Atlas (TCGA) database showed that breast and ovarian cancer patients with high YBX1 expression showed poor prognosis with shorter recurrence-free survival." (PMID 38003589, 2023). "It is reported that activated FAK regulated Y-box binding protein 1 to induce paclitaxel resistance in ovarian cancer while FAK inhibitor could reduce the resistance." (PMID 36176444, 2022). "Interestingly, YBX1 can be found in exosomes secreted by normal and malignant cells as well, like B cells, hepatocytes, prostate, colorectal, and ovarian cancer cells." (PMID 33391635, 2020). "Thus, our study delineates a NSUN2-E2F1-NSUN2 loop regulated by m5C modification in a manner dependent on YBX1 phase separation, and this previously unidentified pathway could be a promising target for ovarian cancer treatment." (PMID 38424195, 2024). "Furthermore, high YBX1 expression was correlated with poor prognosis in breast and ovarian cancers." (PMID 38003589, 2023). "NSUN2 promotes E2F1 expression in an m5C-dependent manner that is also dependent on YBX1 phase separation, and E2F1 can regulate NSUN2 transcription, thus forming the NSUN2-E2F1-NSUN2 feedback loop and providing a promising target for ovarian cancer therapy." (PMID 38424195, 2024). "In ovarian cancer, NSUN2 and YBX1 are amplified and upregulated, and higher expression of NSUN2 and YBX1 predicts a worse prognosis for ovarian cancer patients." (PMID 38424195, 2024). "The colocalization of cytoplasmic SIAH1 and YBX-1 in ovarian cancer cells was detected by confocal microscopy, supporting the direct interaction between SIAH1 and YBX-1 proteins." (PMID 35273154, 2022). "Therefore, we analyzed the expression of YBX1, which is responsible for the sEVs-mediated secretion of SATII RNA to the extracellular matrix, using datasets on breast and ovarian cancers." (PMID 38003589, 2023). "To further confirm that NSUN2-mediated m5C modification regulates E2F1 expression in a manner dependent on YBX1, we overexpressed NSUN2 in ovarian cancer cells with or without YBX1 expression and assessed the expression of E2F1." (PMID 38424195, 2024).